ENSG00000283189 (novel protein)
Gene: Protein-coding gene on chromosome 3 (49,416,777 to 49,429,314, reverse strand). Ensembl gene ENSG00000283189.
Genetic constraint (gnomAD): Loss-of-function variants: 30 observed, 49.76 expected, observed/expected ratio (o/e) 0.6, 90% interval 0.45 to 0.82. Missense variants: 561 observed, 645.89 expected, observed/expected ratio (o/e) 0.87, 90% interval 0.81 to 0.93. Synonymous variants: 242 observed, 257.88 expected, observed/expected ratio (o/e) 0.94, 90% interval 0.84 to 1.04.